ATG101 (autophagy related 101)
Description:
Autophagy factor required for autophagosome formation. Stabilizes ATG13, protecting it from proteasomal degradation.
Synonyms: C12orf44; FLJ11773
Tractability: Small molecule: a structure with a bound ligand is known. PROTAC: ubiquitination databases record sites on it; its protein half-life has been measured.
Gene: Protein-coding gene on chromosome 12 (52,069,246 to 52,077,495, forward strand). Ensembl gene ENSG00000123395.
Subcellular location: Cytoplasm; Preautophagosomal structure
Pathways (Reactome):
Autophagy: Macroautophagy
Gene Ontology:
Molecular function: identical protein binding; protein binding; protein-containing complex binding; protein kinase binding
Biological process: autophagosome assembly; negative regulation of cell population proliferation; regulation of protein lipidation; autophagy; positive regulation of autophagy
Cellular component: Atg1/ULK1 kinase complex; cytoplasm; phagophore assembly site; cytosol; endoplasmic reticulum membrane
Genetic constraint (gnomAD): Loss-of-function variants: 6 observed, 17.39 expected, observed/expected ratio (o/e) 0.35, 90% interval 0.19 to 0.68. The upper end of that interval is the gene's LOEUF score, 0.68, which puts it in group 2 of 6, group 1 being the genes least tolerant of losing a copy. Missense variants: 200 observed, 307.45 expected, observed/expected ratio (o/e) 0.65, 90% interval 0.58 to 0.73. Synonymous variants: 108 observed, 124.45 expected, observed/expected ratio (o/e) 0.87, 90% interval 0.74 to 1.02.
Homologues: Orthologues: chimpanzee ATG101 (100% identical), guinea pig ATG101 (100% identical), macaque ATG101 (100% identical), dog ATG101 (99% identical), pig ATG101 (99% identical), mouse Atg101 (99% identical), rat Atg101 (98% identical), rabbit ATG101 (95% identical), tropical clawed frog atg101 (91% identical), zebrafish atg101 (87% identical), Drosophila melanogaster Atg101 (51% identical), Caenorhabditis elegans epg-9 (37% identical).
Diseases named in the same sentence as ATG101 in open-access papers:
ATG101 is named in the same sentence as 21 diseases in open-access papers, as found by Europe PMC text mining. Sharing a sentence is not in itself a finding about the gene and the disease. The quoted sentences say what the papers report.
cholangiocarcinoma (1 paper, 2022). A carcinoma that arises from the intrahepatic biliary tree (intrahepatic cholangiocarcinoma) or from the junction, or adjacent to the junction, of the right and left hepatic ducts (hilar cholangiocarcinoma). "The expression of ATG101 was further verified by cholangiocarcinoma (CHOL) cell lines." (PMID 35592424, 2022). "More importantly, in our unpublished microarray data, we found that PDT can induce the differential expression of ATG101 in gastric cancer, colorectal cancer and cholangiocarcinoma, so ATG101 may also be a common target for tumor immunity and photodynamic therapy." (PMID 35592424, 2022). "Subsequent validation tests confirmed that the up-regulated ATG101 after PDT treatment is not conducive to the occurrence of apoptosis of cholangiocarcinoma cells." (PMID 35592424, 2022).
colon cancer (1 paper, 2021). "We obtained the risk score of each case with colon cancer; risk score = (0.46121 × expression of ULK3) + (0.650715 × expression of ATG101) + (1.521474 × expression of MAP1LC3C) + (0.641122 × expression of TSC1) + (0.243022 × expression of DAPK1) + (-0.17015 × expression of SERPINA1)." (PMID 34315829, 2021). "The results suggested that ATG101 and TSC1 levels in colon cancer tissues were significantly higher than normal tissues." (PMID 34315829, 2021). "We identified 6 prognostic-related ARGs (ULK3, ATG101, MAP1LC3C, TSC1, DAPK1 and SERPINA1) to formulate a novel autophagy-related signature, which could stably predict the survival of patients and indicate the extent of immunosuppressive microenvironment in colon cancer." (PMID 34315829, 2021).
colorectal cancer (1 paper, 2022). A primary or metastatic malignant neoplasm that affects the colon or rectum. "In our previous microarray data, it was found that many tumors including CHOL and colorectal cancer, up-regulated ATG101 after PDT treatment." (PMID 35592424, 2022). "Moreover, ATG101 is essential for tissue homeostasis in both adult brains and midguts and mediates GSN and OAS2, which are positively and negatively associated with the recurrence of colorectal cancer, respectively." (PMID 35592424, 2022).
nematode infection (1 paper, 2025). "Several autophagy-related genes (ATG101, ATG4b, ATG8a, ATG8b, ATG8c, ATG18a, Tap46) were significantly upregulated in the cultivar 685 upon nematode infection, suggesting their involvement in enhancing resistance to M. graminicola." (PMID 40508124, 2025).
pancreatic cancer (1 paper, 2021). "To identify upstream E3 ubiquitin ligases targeting ATG101, we first screened for ATG101-interacting proteins in MIA PaCa-2 pancreatic cancer cells using immunoprecipitation and mass spectrometry." (PMID 34502089, 2021).
pulmonary hypertension (1 paper, 2020). Increased pressure within the pulmonary circulation due to lung or heart disorder. "ATG101 is an essential gene for the initiation of autophagy and may be involved in endothelial cell growth through regulation of autophagy in pulmonary hypertension." (PMID 31999706, 2020).
cancer (5 papers, 2021 to 2023). A tumor composed of atypical neoplastic, often pleomorphic cells that invade other tissues. "Taken together, these results indicate that the most common cancer-associated CTD truncation mutants are loss-of-function for autophagy regulation by loss of interaction with ATG101." (PMID 36672319, 2023). "In this study, we present evidence for the first time that mutations in the CTD of PTCH1 prevent interaction with ATG101 and enhance the proliferation and survival of cancer cells under nutrient stress." (PMID 36672319, 2023). "Immunoprecipitation of the PTCH1 variants using the common myc-tag showed that the interaction of ATG101 is abolished in all cancer-associated PTCH1 CTD truncation mutants." (PMID 36672319, 2023). "After pan-cancer analysis, ATG101 was recognized as the risk factor for survival in several cancers including HCC." (PMID 36302799, 2022). "ATG101 expression was significantly positively associated with cancer-associated biological processes such as the cell cycle, recycling of EIF2_GDP, NF-kB signaling, and autophagy, etc.." (PMID 36302799, 2022). "We quantified the levels of various cancer hallmarks and identified ATG101 as the major risk factor for overall survival in HCC." (PMID 36302799, 2022). "Changes in the abundance and mutation profile of ATG101 in various cancers leads to the emergence of new antigenic epitopes." (PMID 35592424, 2022). "In cancer cells, knocking down ATG101 caused significant growth retardation and reduced survival under nutritional deprivation." (PMID 36302799, 2022). "Next, ATG101 showed a significant association with all the cancer hallmarks." (PMID 36302799, 2022). "Moreover, ATG101 expression is associated with immune infiltration in several cancers." (PMID 36302799, 2022). "Pan-cancer analysis showed that 24 out of 31 cancers had considerably greater expression of ATG101 in tumor tissues." (PMID 36302799, 2022). "Our study highlights the significance of ATG101 in the study of tumour immunity and photodynamic therapy from a pan-cancer perspective." (PMID 35592424, 2022). "In this study, we explored for the first time the relationship between ATG101 and different tumours from a pan-cancer perspective." (PMID 35592424, 2022). "First, we compared tumour samples and paracarcinoma tissues from the TCGA database, normal samples from the GTEx database and cancer cells from the CCLE database to evaluate the mRNA expression characteristics of ATG101 in humans." (PMID 35592424, 2022). "First, integrated analysis of The Cancer Genome Atlas and Genotype-Tissue Expression portals were used to analyse the expression of ATG101." (PMID 35592424, 2022). "In cancer cells, HUWE1 targets the ubiquitination and degradation of the C-terminal region of ATG101, inhibiting autophagy activity to reduce cancer cell survival." (PMID 35806307, 2022). "We found that the expression of ATG101 varied in different normal tissues and cancer cells after collating the tumour tissues and paracarcinoma tissues from the TCGA database." (PMID 35592424, 2022). "Our findings provide evidence for ATG101 as an immunotherapy target from a pan-cancer perspective and suggest that ATG101 can be used as a resistance marker for photodynamic therapy." (PMID 35592424, 2022). "We explored the relationship between ATG101 expression and immune infiltration in different tumours after investigating the relationship between ATG101 expression and cancer prognosis." (PMID 35592424, 2022). "Our results demonstrate that HUWE1 destabilizes ATG101 by poly-ubiquitination at the C-terminus, thereby suppressing ATG101-mediated autophagy activity and further inhibiting cancer cell survival under nutrient deprivation conditions." (PMID 34502089, 2021). "Knockout of ATG101 markedly reduced the proliferation rate and survival of cancer cells, especially under nutrient deprivation, strongly suggesting that autophagy is a critical survival mechanism for these cells under metabolic stress." (PMID 34502089, 2021).
cancer (continued). "Here we investigated novel roles for ATG101 ubiquitination in modulating autophagy activity and cancer cell survival." (PMID 34502089, 2021). "Knockout of ATG101 in cancer cells using CRISPR resulted in severe growth retardation and lower survival under nutrient starvation." (PMID 34502089, 2021). "Cellular survival rates were higher in HUWE1-knockdown cancer cells compared to controls, while concomitant siRNA-mediated ATG101 knockdown tends to increase apoptosis rate." (PMID 34502089, 2021). "HUWE1 was identified as an upstream E3 ligase catalyzing ATG101 ubiquitination in cancer cell lines based on the substantial reduction in ubiquitinated ATG101 upon HUWE1 KD." (PMID 34502089, 2021). "We further studied the relationship between ATG101 expression and neoantigens in various cancers." (PMID 35592424, 2022). "Among various hallmarks of cancer, ATG101 expression is mostly correlated with DNA damage." (PMID 36302799, 2022). "The characteristics of ATG101 expression at the mRNA level suggested that ATG101 may be a valuable target for pan-cancer." (PMID 35592424, 2022). "We found that ATG101 was highly correlated with immune checkpoint genes in various cancers." (PMID 35592424, 2022). "Moreover, enhanced autophagy in HUWE1-depleted cancer cells was reversed by siRNA-mediated ATG101 knockdown." (PMID 34502089, 2021). "To directly examine the contribution of impaired autophagy from ATG101 KO to reduced cancer cell proliferation and survival, we measured autophagy activity under nutrient starvation by immunoblotting and subcellular localization of the autophagy marker proteins." (PMID 34502089, 2021). "Thus, ATG101 appears to promote the proliferation and survival of cancer cells, possible by activating or maintaining autophagy, a notion investigated in subsequent experiments." (PMID 34502089, 2021). "Here, we examined whether ULK1 complex component autophagy-related protein 101 (ATG101) is downregulated via ubiquitination, and whether this in turn suppresses autophagy activity in cancer cells." (PMID 34502089, 2021). "Accordingly, we examined whether increased autophagy in HUWE1-depleted cancer cells could be suppressed by knockdown of WIPI2 as well as by ATG101 knockdown." (PMID 34502089, 2021). "Moreover, knockdown of HUWE1 enhanced the rate of LC3 puncta formation in cancer cells under metabolic stress, indicating that this regulatory mechanism for ATG101 levels directly modulates autophagy." (PMID 34502089, 2021). "Finally, we demonstrated that ATG101-mediated autophagy facilitated while ATG101 downregulation by HUWE1-mediated ubiquitination impaired cancer cell survival." (PMID 34502089, 2021). "With the aim to determine whether the truncation mutants retain interaction with ATG101, we performed co-immunoprecipitation studies and demonstrated that none of the cancer-associated mutants binds ATG101." (PMID 36672319, 2023). "In addition, we analyzed the relationship between ATG101 and immune cells, common immune checkpoint genes, and microenvironment scores, as well as the relationship between ATG101 expression levels and methyltransferase expression in various cancers." (PMID 35592424, 2022). "ATG101 may be a potential target for immunotherapy of these cancers." (PMID 35592424, 2022). "Accordingly, ATG101-mediated autophagy may play a critical role in overcoming metabolic stress, thereby contributing to the growth, survival, and treatment resistance of certain cancers." (PMID 34502089, 2021). "Thus, activation of this HUWE1/ATG101 pathway may be a feasible clinical strategy to impair cancer cell survival or enhance the efficacy of anti-tumor therapies." (PMID 34502089, 2021). "However, further research is still needed to explore ATG101 epigenetic changes and its potential functions, which may contribute to the development of new cancer treatments and the discovery of new markers to predict the prognosis of patients with cancer." (PMID 35592424, 2022).
cancer (continued). "Overall, our data indicates that modulation of ATG101 protein levels by HUWE1-mediated ubiquitination and ensuing changes in autophagy activity influence the survival of cancer cells under metabolic stress." (PMID 34502089, 2021). "Protein levels of ATG101 was more stable and the related-autophagy activity was higher in HUWE1-depleted cancer cells compared to wild type (WT) controls, indicating that HUWE1-mediated ubiquitination promotes ATG101 degradation." (PMID 34502089, 2021). "Further, double knockdown of both ATG101 and WIPI2 in shHUWE1 cancer cells significantly increased the apoptotic death rate compared to that in shCTL cells." (PMID 34502089, 2021). "Collectively, these results suggest that HUWE1 normally serves to suppress autophagy by ubiquitinating and triggering degradation of ATG101 and WIPI2, which in turn represses the survival of cancer cells." (PMID 34502089, 2021). "Similar to ULK1, ATG101 in the same complex for autophagy initiation, the protein levels were gradually reduced in MIA PaCa-2 and HeLa cancer cell lines by treatment with the protein synthesis inhibitor cycloheximide (CHX)." (PMID 34502089, 2021). "Here, we examined whether the ULK1 complex component ATG101 is also regulated by ubiquitination, and conducted additional experiments to identify the types of ubiquitin-conjugation and enzymes involved, as such information could help define therapeutic targets for autophagy modulation in cancer." (PMID 34502089, 2021). "Therefore, we further used Kaplan–Meier analysis to explore the correlation between ATG101 mRNA expression levels and the survival outcomes (including the OS, DSS, DFS and PFS rates) of different cancers from the TCGA database." (PMID 35592424, 2022). "We also researched the correlation between ATG101 expression and MSI in various cancers." (PMID 35592424, 2022). "Due to this reciprocal regulation of ATG101 and HUWE1, ATG101-mediated autophagy activation under HUWE1 depletion may overcome the metabolic stressors frequently encountered by cancer cells." (PMID 34502089, 2021). "However, there are no studies on the significance of ATG101 in pan-cancer or its role in the immune microenvironment." (PMID 35592424, 2022). "This indicates that there is a significant negative correlation between ATG101 expression and MSI and TMB in these cancers." (PMID 35592424, 2022).
tumor (4 papers, 2021 to 2023). "If this is the case, mutations in the CTD that jeopardize the binding of ATG101 should impair the tumour suppressor function of PTCH1." (PMID 36672319, 2023). "Kaplan–Meier curves found that ATG101 was associated with poor prognosis in tumours (including CHOL and LIHC)." (PMID 35592424, 2022). "Association between ATG101 expression with clinical parameters suggested the potential tumor marker of ATG101 in HCC." (PMID 36302799, 2022). "Therefore, ATG101 is expected to be a diagnostic and prognostic marker of different tumours." (PMID 35592424, 2022). "Based on the correlation between immune cells and ATG101 expression, we also explored the relationship between ATG101 expression and the tumour immune microenvironment." (PMID 35592424, 2022). "With the cut-off of p value of 0.05, ATG101 expression was positively correlated with tumour-infiltrating immune cells." (PMID 35592424, 2022). "Here, our study aimed to elucidate the correlation of ATG101 expression with tumor prognosis and its potential roles and mechanisms in tumor immunity and photodynamic therapy (PDT)." (PMID 35592424, 2022). "Our research aims to illustrate the correlation between the expression of ATG101 and tumor prognosis and its potential role and mechanism in tumor immunity and photodynamic therapy (PDT)." (PMID 35592424, 2022). "We found that ATG101 can be used as a target and prognostic marker of tumour immunotherapy for different tumours." (PMID 35592424, 2022). "Autophagy related gene 101 (ATG101) plays a significant role in the occurrence and development of tumours by responding to stress." (PMID 35592424, 2022). "In this study, we found that the correlation between the expression levels of DNA methyltransferase and ATG101 varied in different tumours." (PMID 35592424, 2022). "Comprehensive analysis showed that ATG101 was overexpressed in different tumours." (PMID 35592424, 2022). "Inhibiting ATG101 on the basis of PDT can increase the anti-tumor effect." (PMID 35592424, 2022). "Following our findings that PTCH1 reduces autophagic flux through its CTD, we hypothesised that its interaction with ATG101 is important for the tumour suppressor activity of PTCH1, which is mainly ascribed to its function to reduce GLI1 levels via regulation of the canonical Hh pathway." (PMID 36672319, 2023). "Thus, either the HUWE1/ATG101 or HUWE1/WIPI2 pathway could be potential targets for suppressing tumor cell survival, and these reverse combinational approaches may be more effective." (PMID 34502089, 2021). "In contrast, the Hedgehog (Hh) receptor Patched1 (PTCH1) was shown to bind ATG101 through the PTCH1 C-terminal domain and inhibit autophagy flux, which further influences PTCH1-dependent tumor suppression independent of Sonic Hedgehog canonical signaling." (PMID 34502089, 2021).
infection (1 paper, 2021). The state of being infected such as from the introduction of a foreign agent such as serum, vaccine, antigenic substance or organism. "Our study showed that the expression of autophagy-related genes ULK1, ATG13, ATG101, Beclin-1, ATG14, MAP1LC3A, and MAP1LC3B was significantly increased and that SQSTM1 was decreased in the muscle with pathogen infection." (PMID 33574492, 2021).
ATG101 also shares sentences with these, for which no sentence is quoted: alcoholic liver diseases (1 paper); breast carcinoma (1); breast tumors (1); colon adenocarcinoma (1); diabetic kidney disease (1); gastric cancer (1); hepatocellular carcinoma (1); liver cancer (1); Pan (1); protein folding disorders (1); renal fibrosis (1); viral infection (1).